CD27 (CD27 molecule)
Diseases named in the same sentence as CD27 in open-access papers (continued):
Sharing a sentence is not in itself a finding about the gene and the disease.
autoimmune disease (46 papers, 2009 to 2025). A disorder resulting from loss of function or tissue destruction of an organ or multiple organs, arising from humoral or cellular immune responses of the individual to their own tissue constituents. "Surface expression of CD70 has been associated with a higher risk of cancer malignancy and aberrant T-cell activation in part due to CD70/CD27 interactions that can induce excessive infiltration of T cells and cause autoimmune disease." (PMID 35216458, 2022). "A comparable rise in CD27-CD38lowCD21low B-cells was noted in patients with pSS, a typical B-cell-associated autoimmune disease." (PMID 34168654, 2021). "In conclusion, we showed that the frequencies of CD27-CD38lowCD21low B-cells are elevated in axSpA, similar as observed in an established B-cell-associated autoimmune disease, pSS." (PMID 34168654, 2021). "In a mouse model of autoimmune disease, Th17 comprised two subsets, CD27+ stemness-associated and CD27−/T-bet+ able to trans-differentiate into Th1-like cells." (PMID 31134070, 2019). "Rotavirus (RV) memory B cells (mBc) are enriched in IgM+ and CD27- subpopulations, which are associated with autoimmune diseases pathogenesis." (PMID 24819618, 2014). "Notably, the CD27/CD70 signaling pathway has been extensively linked to the promotion of autoimmune diseases, whereas CD52 has been associated with inflammation suppression, suggesting that DCs may exert a dual mode of action on T cells." (PMID 38596682, 2024). "Based on the definition of B cells subsets in previous studies of various autoimmune diseases, B cells are classified as CD27− B cells and CD27+ B cells indicating a subset of B cells that experienced antigen stimulation." (PMID 41177827, 2025). "Biomarkers, including CD19+ B cells or CD27+ B cells in the peripheral blood, have been used to guide rituximab redosing in different autoimmune diseases such as rheumatoid arthritis, with varying success." (PMID 41007719, 2025). "This phenotype resembles a population of CD27+CD24hi B cells previously identified in patients with autoimmune disease and defined as potential memory B cells." (PMID 39324141, 2024). "An increased ratio of naïve (CD27-IgD+) to memory (CD27+) B-cells has also been reported in other autoimmune diseases including Sjögren’s syndrome and systemic sclerosis and is therefore not specific for PAPS." (PMID 36614819, 2022). "In many autoimmune diseases, the CD27+ B cell fraction, memory B cells, is enriched with autoantigen-reactive B cells." (PMID 34854378, 2021). "In autoimmune diseases, large expansions in IgD− IgM+ CD27+ and IgG− CD27+ phenotypes, which dominantly employ IgG1 and IgG3, the powerful activators of complement and are implicated in target destruction by ADCC." (PMID 34539411, 2021). "A decrease in circulating memory B cells and a predominance of CD27-naïve B cells have been reported in these autoimmune diseases, including the very early stages of RA and other polyarthritis." (PMID 32973793, 2020). "We found that these MBCs were activated and expressed the classic memory marker, CD27, excluding them from the IgD-CD27− atypical MBCs described in other autoimmune diseases." (PMID 31340153, 2019). "Dsg3-specific cells expressed the classical MBC marker CD27, excluding these cells from the atypical IgD-CD27− MBCs described in other autoimmune diseases." (PMID 31340153, 2019). "Since many published studies on B cell subsets in pSS and other autoimmune diseases define memory B cells as CD19+CD27+, we also looked at this subset." (PMID 25790192, 2015). "CD27+IgD+IgM+ mBc (IgM+ mBc) and CD27- mBc, the mBc subsets in which RV-mBc are enriched, are relevant in autoimmune diseases pathogenesis." (PMID 24819618, 2014). "Abnormal distributions of peripheral B cell subsets, particularly of CD27+ memory B cells, have been reported in several autoimmune diseases including RA." (PMID 19500335, 2009).
autoimmune disease (continued). "Given the contribution of the CD27 pathway in Th1- and Tc1-mediated pathogenesis of various inflammatory and autoimmune diseases, and graft rejection, AZM may serve as adjunct therapy against these anomalies." (PMID 39211048, 2024). "CD27 memory B cells are increased in the elderly and in patients with specific autoimmune diseases." (PMID 36544777, 2022). "Notably, PD1+ CXCR5+ CD8 T cells in chronic viral infection and progenitor exhausted CD8 T cells from the tumors as well as CD27+ Th17 cells from autoimmune disease display stemness." (PMID 33370392, 2020). "sCD27 has been related to membrane CD27 expression on activated lymphocytes, and used to monitor systemic immune activation in a variety of immunological disorders such as chronic viral infections, autoimmune diseases and B cell malignancies." (PMID 25111833, 2014). "FcRH4- CD27- switch memory B cells may be more responsive to activation and may expand more easily in autoimmune diseases than their CD27-, FcRH4+ counterparts, because FcRH4 is a potent inhibitor of B-cell signaling." (PMID 19804628, 2009). "Furthermore, upon binding of CD70 to CD27, soluble CD27 (sCD27) is cleaved off by metalloproteinases and has been detected in serum, plasma, and urine samples from healthy individuals, and at increased levels in patients with autoimmune diseases." (PMID 25951351, 2015). "The positive association between CD19+CD27+ B-cell frequency and serum 25(OH)D3 in NMOSD after immune-cell stimulation must also be further explored to establish whether vitamin D does have beneficial effects in this autoimmune disease, or if this was simply an accidental correlation." (PMID 34394078, 2021). "In our analysis, we did not observe differences in the percentage of IgD+IgM− subset in CD27− B cells between patients with or without autoimmune diseases and healthy subjects." (PMID 38392874, 2024). "We also evaluated the compartment of CD27+ B cells according to the presence or not of autoimmune diseases, and CVID patients with autoimmune disease showed a higher percentage of IgD+IgM+ and IgD−IgM+ CD27+ B cells compared with the control." (PMID 38392874, 2024). "Special emphasis was given to CD27-negative B-cells expressing low levels of CD21 (CD21low B-cells), since this subset is implicated in autoimmune diseases with strong involvement of B-cells." (PMID 34168654, 2021). "Whereas CD27+ memory B cells arise through germinal center reactions, CD27- IgD- memory B cells (increased in the autoimmune disease, SLE) do not." (PMID 34234784, 2021). "Findings from the RRA discovery study suggested that CD160 was the most significant gene aberrantly expressed in autoimmune diseases (Adjusted P = 5.9E-12), followed by CD58 (Adjusted P = 5.7E-06), CD244 (Adjusted P = 9.5E-05), LGALS9 (Adjusted P = 0.001) and CD27 (Adjusted P = 0.005)." (PMID 30842773, 2019). "Besides the case of HIV-1 gp120, another example was also illustrated based on human glycoprotein antigens of CD27 (PDB ID: 5TLK Chain: X), which is an important antibody drug targets for autoimmune diseases and cancers." (PMID 31114919, 2019). "Several correlations between CD27 and other MAIT cell variables, such as a positive correlation with MAIT cell frequency and negative correlations with CD69 and PD1 expression by MAIT cells, were only observed in the women with long-term type 1 diabetes and another autoimmune disease." (PMID 34350463, 2021). "To date, the characterization of the B-cell phenotype with multiparameter flow cytometry has identified several B-cell subpopulations, including CD27+IgD+ non-switched memory B cells and CD27+IgD− switched memory B cells, which may represent a biomarker for some autoimmune diseases." (PMID 38339108, 2024).
autoimmune disease (continued). "In our analysis of IgD+IgM− subset in CD27+ B cells, we observed a higher percentage of this subset in CVID patients without autoimmune diseases, indicating that IgD+IgM− memory B cells may not have a role in the presence of autoimmune diseases in CVID patients." (PMID 38392874, 2024).
melanoma (43 papers, 2010 to 2026). A malignant, usually aggressive tumor composed of atypical, neoplastic melanocytes. "Key findings include BAFF-R on B cells lowering melanoma risk, and CD27 on B cells increasing lung cancer risk." (PMID 41623454, 2026). "For instance, the persistence of melanoma-reactive T cells in patients with metastatic melanoma receiving ACT has been associated with their expression of CD27, suggesting a linkage between this differentiation marker and antitumor memory CD8+ T cells." (PMID 33208551, 2020). "In concordance with regulatory properties of TGF-β+ Bregs, Kaplan–Meier survival analysis of our melanoma patient cohort indicated that higher levels of circulating TGF-β-expressing CD19+ CD38int IgD+ CD27− PD-L1+ naïve B cells were associated with less favorable overall survival (N = 18)." (PMID 35909944, 2022). "The CD27+CD11b- NK subset of cells was increased in all three melanoma groups compared to healthy mice (PBS and IMQ, p < 0.001; and GDQ, p < 0.05, respectively)." (PMID 41597427, 2026). "Accordingly, we observed more memory T cells (CD3+ CD27+) in the Melanoma-Combi-ICI group compared to controls." (PMID 40313772, 2025). "While activation of CD27 in a murine melanoma model reduced the development of distant metastasis, in human ER-negative breast cancers activated T cells were shown to promote the rise of brain metastases." (PMID 40621453, 2025). "We have shown that the tumor of melanoma patients is well infiltrated by CD8+ T lymphocytes expressing CD27, which interacts with the CD70 molecule." (PMID 40148586, 2025). "In this study, we first characterized the intratumoral expression of CD70 and CD27 in melanoma tumors and their interaction in vivo." (PMID 40148586, 2025). "Within the CD27+ IFNγ-producing γδ T-cell subset, there appears to be some nuance, as Vγ4+ cells are better at restraining B16 melanoma tumors than Vγ1+ cells." (PMID 38816652, 2024). "After confirming specific deletion of CD27 from CD8 + cells, we sought to investigate the B16-F10 melanoma tumor growth in both global CD27 KO and CD8Cre-CD27fl mice." (PMID 39105866, 2024). "In a murine melanoma model, anti-CD27 agonistic mAb treatment potentiated tumor control by increasing the frequency and maximal activity of tumor-specific CD8+T-cell and NK cells in the TME." (PMID 37345056, 2023). "WT and B2m-/- B16 melanoma challenge significantly reduced the IVneg proportions of DN and CD11b-CD27+ precursors and increased functionally dynamic and mature NK cell populations comprising DP and CD11b+CD27- NK cells." (PMID 36733396, 2022). "In some CD27 mAb-treated melanoma patients, increased numbers of T cells that recognize melanoma-related antigens were revealed." (PMID 36700229, 2022). "Two CD27 agonists have already entered clinical trials with patients suffering from malignancies including lymphomas, melanoma, and renal cell carcinoma." (PMID 33180337, 2021). "The anti-tumor effect of CD27 ligation has been demonstrated in murine B cell lymphoma and melanoma models, and preliminary results of the phase I studies of the anti-human CD27 mAb, varlilumab demonstrate that it is well tolerated and has anti-tumor efficacy." (PMID 29198913, 2017). "The effects of co-colture with melanoma cells was next evaluated on CD8+CD27+CD45RA+ naïve T cells, CD8+CD27+CD45RA− memory T cells and CD8+CD27−CD45RA− effector T cells." (PMID 26329660, 2015). "The inhibitory effects exerted by melanoma cells were tested on CD4+CD27+CD45RA+ naïve T cells, CD4+CD27+CD45RA− central memory T cells and CD4+CD27−CD45RA− effector memory T cells." (PMID 26329660, 2015). "Studies at the National Cancer Institute (Bethesda, MD) have demonstrated that in melanoma patients receiving ACT, the total number of CD8+CD27+ TIL administered to patients was associated with improved clinical responses." (PMID 23560068, 2013).
melanoma (continued). "Also, topical administration resulted in an increased expression of some markers for NK cell activation and maturation, such as CD69, NKp46, CD122, CD11b, CD43, KLRG1, and CD27, when compared with melanoma-bearing mice." (PMID 41597427, 2026). "On the other hand, an increased CD57+CD27+ CD8 T subset among melanoma TIL could proliferate in response to IL-2 and differentiate into CD57+CD27– T with increased perforin expression and potent anti-tumor cytotoxicity." (PMID 40868094, 2025). "Therefore, these experiments with the B16-F10 melanoma model indicate that endogenous CD27 signaling in the host inhibits tumor growth via CD8 + T cell-independent mechanisms." (PMID 39105866, 2024). "During treatment, higher proportions of 41BB+ Tconv cells, LAG3+ γδ2–T and TIGIT+ iNKT cells were observed in R compared to NR patients, while frequencies of GITR-expressing γδ2–T and iNKT, 41BB-expressing NKbright and CD27-expressing NKdim cells were decreased in responder melanoma patients." (PMID 39687620, 2024). "Additionally, the potential value of various new inhibitory immune checkpoints (BTLA, B7 family, IDO-1, LAG-3) and costimulatory molecules (GITR, ICOS, OX40, 4-1BB, CD40, CD27) has been confirmed for melanoma treatments." (PMID 36125617, 2022). "Our current study revealed that an interaction between CD27 and CD70 in the TME of melanoma patients, with CD70 primarily expressed by stromal cells in this context." (PMID 40148586, 2025). "In line with this, we observed a significant increase in T cells in the brains of melanoma-bearing mice receiving Combi-ICI, particularly memory phenotype (CD27+)." (PMID 40605058, 2025). "We used the CD8Cre-CD27fl mice along with the global CD27 KO mice to study how selective CD27 deletion from CD8 + T cells and global CD27 KO affect tumor growth and metastasis in the B16-F10 melanoma model." (PMID 39105866, 2024). "Treatment of 25 (Melanoma, CRC, OC, PC, RCC, NSCLC) and 31 patients (melanoma, RCC), with varlilumab (alias: CDX-1127), a fully humanised agonistic CD27 IgG1 mAb, in a phase 1 dose-escalation and -expansion trial, respectively was well tolerated." (PMID 38440738, 2024). "Based on clinical outcomes observed in melanoma patients treated with TILs, the CD8+/CD4+ ratio and the number of CD8+CD27+ T cells infused in these patients correlated with their response to treatment." (PMID 33208551, 2020). "We used seven-color multiplex immunostaining (CD20, CD19, CD5, CD27, CD38, CD138, and DAPI) to approximate six different TAB subpopulations in whole tissue sections of melanoma metastases from 41 different patients." (PMID 31519915, 2019). "Both CD27+ and CD11b+ NK cells from laquinimod-treated animals killed B16F10 melanoma cells more efficiently than CD27+ and CD11b+ NK cells from vehicle-treated controls." (PMID 30808363, 2019). "We also examined anti-CD27 with another direct tumor-targeting mAb, anti-gp75, in the B16F10 melanoma model, where peritoneal metastases were assessed on day 13 after tumor inoculation." (PMID 29198913, 2017). "Increased values were also observed for CD27 and B220 compared to the control group, but not the melanoma group, while KLRG1 expression was higher than for the melanoma group, approaching that of healthy animals." (PMID 41597427, 2026). "In addition, melanomas with brain metastases (BM) showed higher expression levels of fibronectin, CTLA-4, CD27, and PanCK compared to tumors with metastases in other organs (OOM)." (PMID 40621453, 2025). "In conclusion, this study demonstrates that endogenous CD27 signaling in the host inhibits tumor growth and metastasis via CD8 + T cell-independent mechanisms in the B16-F10 melanoma model, presumably through stimulating antitumor activities of other types of immune cells." (PMID 39105866, 2024).
melanoma (continued). "A specific subset of infiltrating B cells are strong prognostic factors in various cancers context, such as CD20+ CD27− IgM+ group and CD20+ CD27− IgM− group in hepatocellular carcinoma(HCC), IgG4+ in pancreatic ductal adenocarcinoma and CD20+ in melanoma and some other cancers." (PMID 32518520, 2020). "Unlike CD4+ and CD8+ T cells observed in melanoma patients, T cells observed in breast tumors showed differential expression of the CD27 cell surface marker, where only half of the CD28+ cells were also positive for cell-surface CD27." (PMID 31417550, 2019). "Finally, our data indicate that anti-CD27 is also effective in enhancing direct tumor-targeting mAbs beyond anti-CD20, such as anti-gp75 in a melanoma model." (PMID 29198913, 2017). "Melanoma TIL consists mostly of activated TCRαβ+ CD4+ and CD8+ T cells with heterogeneous phenotypes ranging from less differentiated effector-memory cells to more differentiated cells that have lost critical co-stimulatory molecules, such as CD27 and CD28." (PMID 23560068, 2013). "Tail vein injections of WT and B2m-/- B16 melanoma cells did not alter the CD11b+ mature NK cell dominance, but it significantly decreased IVpos DP population and likely led to their conversion into CD11b+CD27- NK cells in the circulation." (PMID 36733396, 2022). "Our results have unveiled that, while endogenous CD27 signaling in the host is important for antitumor immune response, specific deletion of CD27 from CD8 + T cells does not change tumor growth and metastasis in this commonly used melanoma model." (PMID 39105866, 2024).